ABCA4 (ATP binding cassette subfamily A member 4)
Diseases named in the same sentence as ABCA4 in open-access papers (continued):
Sharing a sentence is not in itself a finding about the gene and the disease.
ovarian carcinoma (4 papers, 2015 to 2025). A malignant neoplasm originating from the surface ovarian epithelium. "Overexpression of ABCA4 is associated with a complete chemotherapy response in advanced stages of ovarian carcinoma, which suggests that there is a positive effect on its overexpression in AR‐357‐treated LNCaP and PC3 cells." (PMID 40181576, 2025).
geographic atrophy (3 papers, 2023 to 2025). "Discrepancies between the blue and green FAF modalities have been reported in the literature for healthy eyes and several pathologies, including geographic atrophy, ABCA4 retinopathy, and various other retinochoroidopathies." (PMID 40423615, 2025).
hereditary macular dystrophy (3 papers, 2021 to 2024). Macular dystrophy that is related to a change in a gene. "This has prevented its ready application in the treatment of common retinopathies caused by genes with longer coding sequences, such as the ABCA4 gene (6.8-kb), which is the most common cause of hereditary macular dystrophy." (PMID 34768969, 2021).
myopia (3 papers, 2018 to 2025). "In addition, a missense variant c.1268A>G in ABCA4 was recently found to be responsible for myopia." (PMID 30245926, 2018). "In addition to the novel mutations found in five known myopia genes (ADAMTS18, CSMD1, P3H2, RPGR, and SLC39A5), we also identified pathogenic variants in seven ocular disease genes (ABCA4, CEP290, HSPG2, PCDH15, SAG, SEMA4A, and USH2A) as novel candidate genes." (PMID 30245926, 2018). "These eyes had a mean refractive error of −4.50 ± 4.49D (range −0.25–−11.13D) and three of these patients (25%; ABCA4, COL2A1, KCNV2) had high myopia." (PMID 41465105, 2025).
ocular albinism (3 papers, 2020 to 2025). Albinism affecting the eye in which pigment of the hair and skin is normal or only slightly diluted. "These patients exhibited ABCA4-associated changes such as bull’s eye maculopathy and retinal mosaic patterns characteristic of Nettleship-Falls type ocular albinism (OA1)." (PMID 40269797, 2025).
Retinal atrophy (3 papers, 2019 to 2025). A nonspecific term denoting wasting, especially as a result of degeneration, of the retinal pigment epithelium (RPE) and neurosensory retinal cells. "More importantly, intravitreal injection of apo-TRF effectively rescued retinal function and alleviated retinal atrophy in Abca4−/−Rdh8−/− mice after exposure to light, and it clearly increased the production of atRAL-dimer and A2E in posterior eyecups." (PMID 39653244, 2024). "Sparing of the peripapillary AF was classically considered as pathognomonic and constant in ABCA4-related diseases, even at the late stages with extensive retinal atrophy." (PMID 31574917, 2019). "Moreover, previous reports indicate that the photoreceptor-specific all-trans-retinol dehydrogenase 8 (Rdh8) is an assistant susceptibility gene for STGD1 and dry AMD, and its knockout accelerates retinal atrophy in Abca4 mutant mice." (PMID 39984833, 2025). "Rdh8 is considered as an assistant susceptibility gene for STGD1 and dAMD, and its knockout in mice does not incite the degeneration of retina but slows the reduction of atRAL to atROL in the visual (retinoid) cycle and accelerates retinal atrophy in Abca4 mutant mice." (PMID 39653244, 2024).
Alzheimer disease (2 papers, 2016 to 2022). A progressive, neurodegenerative disease characterized by loss of function and death of nerve cells in several areas of the brain leading to loss of cognitive function such as memory and language. "ABCA1/ABCA7 is bound up with Alzheimer’s disease, ABCA4 is in connection with Stargardt macular degeneration, and ABCC8/SUR1 and ABCC9/SUR2 are both associated with diabetes." (PMID 35783291, 2022). "ABCA4 is a causal gene for Stargardt disease, a retinopathy whose clinical symptoms overlap with AMD; APOE is a gene associated with Alzheimer’s disease (AD), a neurological degenerative disorder, whose pathology overlaps with AMD." (PMID 27329102, 2016).
autosomal dominant Stargardt-like macular dystrophy (2 papers, 2021 to 2022). "The onset of clinical symptoms in PRPH2-associated autosomal dominant Stargardt-like macular dystrophy was reported to start later in life (≥50 years old), which could have allowed to distinguish them from the ABCA4 and ELOVL4 patients." (PMID 34073554, 2021).
central areolar choroidal dystrophy (2 papers, 2009 to 2025). "In the other case, the absence of ABCA4 mutations led to the retrospective diagnosis of central areolar choroidal dystrophy." (PMID 20029649, 2009).
congenital toxoplasmosis (2 papers, 2008). Toxoplasma infection that is present from birth. "These associations between clinical outcomes of congenital toxoplasmosis and polymorphisms at ABCA4 and COL2A1 provide novel insight into the molecular pathways that can be affected by congenital infection with this parasite." (PMID 18523590, 2008). "Using these cohorts we show that ocular and brain disease in congenital toxoplasmosis associate with polymorphisms in ABCA4, while polymorphisms at COL2A1 encoding type II collagen associate only with ocular disease." (PMID 18523590, 2008). "We (RM) recently noted that ABCA4, which transports toxic oxidized lipids out of cells, has a susceptibility allele associated with development of hydrocephalus in human congenital toxoplasmosis." (PMID 18947414, 2008). "FBAT analysis under dominant model of inheritance for associations between ABCA4 and COL2A1 and congenital toxoplasmosis in the NCCCTS child-parent trios." (PMID 18523590, 2008). "Overall, our finding that polymorphisms at ABCA4 and COL2A1 are associated with ocular and other manifestations of congenital toxoplasmosis provides novel insight into the molecular pathways that can be affected by congenital infection with this parasite." (PMID 18523590, 2008). "Logistic regression analysis for genotype-wise associations between ABCA4 and COL2A1 and risk of congenital toxoplasmosis in the EMSCOT mother-child pairs." (PMID 18523590, 2008). "Herein we examined the specific genetic hypothesis that polymorphisms in two genes known to be associated with ocular disease, ABCA4 and COL2A1, are associated with ocular disease caused by congenital toxoplasmosis." (PMID 18523590, 2008).
diabetic retinopathy (2 papers, 2016 to 2025). "In diabetic retinopathy, the mechanistic association of ABCA4 dysfunction extends beyond classical photoreceptor pathology." (PMID 41010507, 2025). "This study advances our understanding of diabetic retinopathy pathogenesis by identifying novel genetic variants (ABCA4_rs17110929, MMP2-AS1_rs2576531, FOXP1_rs557869288) and additional loci (MRPS33_rs1533933, DRD2_rs4936270)." (PMID 41010507, 2025). "We discovered a significant three-way interaction among ABCA4_rs17110929, MMP2-AS1_rs2576531, and FOXP1_rs557869288 that substantially increases diabetic retinopathy susceptibility through complementary mechanisms, affecting retinal homeostasis." (PMID 41010507, 2025). "We proposed a synergistic mechanism of ABCA4/MMP2-AS1/FOXP1 in diabetic retinopathy." (PMID 41010507, 2025).
Harlequin ichthyosis (2 papers, 2015 to 2021). Harlequin ichthyosis (HI) is the most severe variant of autosomal recessive congenital ichthyosis (ARCI; see this term). "Examples of ABC A-subfamily disorders include Tangier’s (ABCA1), Alzheimer’s (ABCA2/ABCA7), Stargardt’s (ABCR/ABCA4), and Harlequin Ichthyosis (ABCA12)." (PMID 26295388, 2015).
Nystagmus (2 papers, 2023 to 2025). Rhythmic, involuntary oscillations of one or both eyes related to abnormality in fixation, conjugate gaze, or vestibular mechanisms. "The onset later in life around 5 or 6 years of age, the absence of nystagmus, and the centrifugal distribution and peripapillary sparing (evident on UWF AF imaging) point towards ABCA4-RD rather than LCA." (PMID 38066771, 2023).
occult macular dystrophy (2 papers, 2018 to 2021). "Heterozygous mutations in ABCA4 can produce bull's eye lesions or occult macular dystrophy, but photoreceptor loss does not extend past the arcades and is accompanied by progressive RPE atrophy." (PMID 30116628, 2018).
Stargardt disease 4 (2 papers, 2023 to 2025). Any Stargardt disease in which the cause of the disease is a mutation in the PROM1 gene. "Stargardt disease 4 (STGD4) shares clinical and pathological features with ABCA4-related Stargardt disease type 1 (STGD1) and the atrophic form of AMD, including central photoreceptor degeneration and RPE atrophy." (PMID 41373691, 2025).
albinism (1 paper, 2024). A congenital disorder characterized by partial or complete absence of melanin pigment in the eyes, hair, or skin. "Similar genetic complexity, albeit unrelated to albinism, is observed in Stargardt Disease Type 1 (STGD1), a juvenile macular dystrophy caused by biallelic variants in ABCA4." (PMID 39125459, 2024).
colon carcinoma (1 paper, 2015). "The role of ABCA4 in cancer is largely unknown to date, whereas ABCB10 was previously shown to be expressed in drug-resistant HT-29 colon carcinoma cells." (PMID 25889687, 2015).
Dyschromatopsia (1 paper, 2021). A form of colorblindness in which only two of the three fundamental colors can be distinguished due to a lack of one of the retinal cone pigments. "Indeed, only a minority of patients of the ABCA4 and ELOVL4 cohorts reported photophobia, respectively 44% and 29%, and dyschromatopsia, respectively 11.11% and 14.29%." (PMID 34073554, 2021).
Leber hereditary optic neuropathy (1 paper, 2020). Leber's hereditary optic neuropathy (LHON) is a mitochondrial neurodegenerative disease affecting the optic nerve and often characterized by sudden vision loss in young adult carriers. "In the pediatric cohort, 78.8% of families showed causative variants in autosomal genes (most frequently ABCA4 and BEST1), 20.7% in X-linked genes (most commonly RS1 and RPGR), and 0.5% in mitochondrial genes (associated with Leber hereditary optic neuropathy)." (PMID 32423767, 2020).
macular holes (1 paper, 2025). A hole in the macula of the retina. "We report a case of retinal detachment and macular hole (MH) in a middle-aged patient with both ABCA4 and BEST1 mutations." (PMID 40062075, 2025).
Onset (1 paper, 2021). The age group in which disease manifestations appear. "Childhood-onset STGD was associated with severe visual loss, generalized retinal dysfunction and was due to more severe variants in ABCA4 than those found in adult-onset disease." (PMID 33988224, 2021).
Photophobia (1 paper, 2021). Excessive sensitivity to light with the sensation of discomfort or pain in the eyes due to exposure to bright light. "The other reported symptoms were less common but similar to the ones of the ABCA4 cohort: reading difficulties (1/7, 14.29%), hemeralopia (1/7, 14.29%), photophobia (2/7, 28.57%), color vision deterioration (1/7, 14.29%), and central scotoma (1/7, 14.29%)." (PMID 34073554, 2021).
retinoblastoma (1 paper, 2020). A malignant tumor that originates in the nuclear layer of the retina. "Expression of Rgr is typically linked to RPE and Muller cells, Abca4 to photoreceptors and Rbp3 to photoreceptor and retinoblastoma cells (Entrez)." (PMID 32655363, 2020).
Strabismus (1 paper, 2021). A misalignment of the eyes so that the visual axes deviate from bifoveal fixation. "The cone–rod dystrophy patient (B1), who carried compound heterozygous variants (NM_000350: c.A2894G, p.N965S and c.2063dupA, p.N688fs) in the ABCA4 gene, complained of visual defects with strabismus for 25 years." (PMID 33732702, 2021).
X-linked recessive disease (1 paper, 2024). X-linked recessive form of disease. "In detail, five autosomal dominant (AD) ophthalmic diseases caused by variants in ABCA4, CRYGD, MYOC, RPL1L1, and TGFBI, one AR disease caused by the PDE6B variant, and one X-linked recessive disease caused by the OCRL variant were determined as genetic causes." (PMID 38785568, 2024).
retinopathy (106 papers, 2005 to 2026). "This case is noteworthy due to the striking preservation of the macula, a feature that is highly atypical for ABCA4 retinopathy and presents a significant diagnostic challenge." (PMID 41458191, 2026). "–7 Biallelic pathogenic variants in the ABCA4 gene cause a range of phenotypically heterogeneous conditions defined as ABCA4-associated retinopathy, the most common inherited Mendelian eye disorder in the world." (PMID 40693713, 2025). "We used CRISPR/Cas9 technology to introduce two ABCA4 missense misfolding variants, T983A and R2077W, which are associated with ABCA4-associated retinopathy, into control induced pluripotent stem cells (iPSCs)." (PMID 40693713, 2025). "Missense variants in ABCA4 constitute ∼60% of causal ABCA4-related retinopathy variants, often resulting in misfolded or dysfunctional protein products." (PMID 40693713, 2025). "The use of retinal organoids to study ABCA4-associated retinopathy has been limited to study variants producing aberrant ABCA4 mRNA." (PMID 40693713, 2025). "Features distinguishing ocular findings in this study from ABCA4-associated retinopathy are foveal sparing, early peripapillary involvement, and reticular pigment clumping in the peripheral retina." (PMID 40081374, 2025). "Complex disease alleles contributed to disease in 16.9% of affected families with ABCA4-associated retinopathy." (PMID 38219857, 2024). "Altogether, the 5 most encountered ABCA4 variants contributed to disease in 50.2% of all families with ABCA4-associated retinopathy." (PMID 38219857, 2024). "The progressive vision loss that affects patients with ABCA4-associated retinopathy is caused by dysfunction of the ABCA4 (ATP-binding cassette subfamily A member 4) protein." (PMID 38892127, 2024). "An analysis of the smMIP sequencing data was performed for 147 ABCA4-associated retinopathy probands." (PMID 38892127, 2024). "These innovative treatments offer exciting possibilities, as gene therapy seeks to correct the underlying genetic mutations responsible for ABCA4 retinopathy by halting or even reversing the disease’s progression." (PMID 39060921, 2024). "ABCA4 whole-gene smMIP-based sequencing was used to analyze 147 ABCA4-associated retinopathy probands in search of causative CNVs." (PMID 38892127, 2024). "ABCA4-associated retinopathy cases are genetically explained by (bi-allelic) single nucleotide variants (SNVs) in the coding regions of the gene or intronic variants affecting splicing (~10%)." (PMID 38892127, 2024). "One hundred sixty-three patients with ABCA4-associated retinopathy underwent WGS via the 100KGP or National Institute for Health Research Bioresource rare disease study with all introns covered." (PMID 38219857, 2024). "ABCA4-related retinopathy is the most common inherited Mendelian eye disorder worldwide, caused by biallelic variants in the ATP-binding cassette transporter ABCA4." (PMID 38674104, 2024). "Several other genes have been associated with clinical presentation similar to ABCA4-retinopathy and are important to consider in differential diagnosis." (PMID 36833218, 2023). "This uniform and improved structured reclassification, incorporating the largest dataset of ABCA4-associated retinopathy cases so far, will improve both the diagnosis as well as genetic counselling for individuals with ABCA4-associated retinopathy." (PMID 40225145, 2023). "Stargardt disease (STGD1), also known as ABCA4 retinopathy, is the most frequent retinal dystrophy caused by a single gene, affecting approximately 1 in 8000 to 10,000 people." (PMID 37728905, 2023). "In the Slovenian registry of patients with ABCA4 retinopathy, c.5714+5G>A is the fourth most frequent variant, present in 12% of patients, which provides an opportunity to perform a detailed phenotypic specification." (PMID 37728905, 2023).
retinopathy (continued). "This knowledge is important for consideration of disease presentation and prognosis as the residual activity of the ABCA4 protein correlates with the severity of ABCA4-associated retinopathy." (PMID 37779911, 2023). "The variant is likely to require other specific cis- or trans-acting modifying factors to cause ABCA4 retinopathy." (PMID 37342033, 2023). "In vitro data overall have to be interpreted with caution, because they often conflict with clinical data in ABCA4-associated retinopathy." (PMID 37728905, 2023). "For ABCA4-associated retinopathy, the variance of AL in the patient group was significantly greater than that for the Raine Study participants (P < 0.001), but not significantly different from the TwinsUK cohort (P = 0.34)." (PMID 35704304, 2022). "Although ABCA4-retinopathy is caused by impaired function of a protein directly associated with vitamin A, there are only a few studies on the impact of vitamin A on its development." (PMID 35162940, 2022). "There is an ongoing extension phase-2 CT examining the tolerability and effects of ALK-001 on Stargardt disease (TEASE), with 140 patients affected by ABCA4-associated retinopathy (NCT04239625), and another CT is in the recruiting phase (NCT02402660)." (PMID 35739983, 2022). "We analyzed 132 eyes from 66 patients (of 67 enrolled) with molecularly confirmed ABCA4-associated retinopathy from a prospective natural history study with a median [IQR] follow-up of 4.2 years [3.1, 5.1]." (PMID 35076026, 2022). "Using a DL-based image segmentation pipeline, this study allowed us to quantify photoreceptor degeneration in ABCA4-associated retinopathy in a large, genetically well-characterized cohort." (PMID 35076026, 2022). "Outcome measures sensitive to disease progression are needed for ATP-binding cassette, sub-family A, member 4–associated (ABCA4-associated) retinopathy." (PMID 35076026, 2022). "This study provides a detailed analysis of the progression of photoreceptor loss over time using SD-OCT in ABCA4-associated retinopathy." (PMID 35076026, 2022). "Macular degeneration omega-3 study (MADEOS) is a CT in the recruiting phase, testing the efficacy of omega-3 fatty acids in AMD and ABCA4-associated retinopathy." (PMID 35739983, 2022). "In summary, we have demonstrated the application of a DL-based pipeline to characterize photoreceptor degeneration over time in ABCA4-associated retinopathy." (PMID 35076026, 2022). "Patients with ABCA4-mediated retinopathies exhibit a strong correlation between visual loss and increased short wavelength (SW) autofluorescence in the RPE due to the presence of bisretinoids." (PMID 36359858, 2022). "More than 1500 variants in the ATP-binding cassette, sub-family A, member 4 (ABCA4), locus underlie a heterogeneous spectrum of retinal disorders ranging from aggressive childhood-onset chorioretinopathy to milder late-onset macular disease." (PMID 34874912, 2022). "In patients with ABCA4-associated retinopathy, the characteristic clinical symptoms of the disease such as macular affection, fundus flecks, and peripapillary sparing can be observed." (PMID 36566289, 2022). "In this regard, an ongoing clinical trial of the National Eye Institute (NEI) is trying to investigate any relationship between risk of HCQ retinopathy and ABCA4 variants." (PMID 35503294, 2022). "Patients with ABCA4-associated retinopathy exhibited significant alterations of photoreceptors outside of EZ-loss." (PMID 35076026, 2022). "It has been suggested that mechanisms involved in ABCA4 retinopathy include secondary photoreceptor loss due to RPE damage, as well as direct cone toxicity." (PMID 36555803, 2022). "We aimed to quantify ellipsoid zone (EZ) loss and photoreceptor degeneration beyond EZ-loss in ABCA4-associated retinopathy and investigate associations between photoreceptor degeneration, genotype, and age." (PMID 35076026, 2022).